TRAF6 (TNF receptor associated factor 6)
Diseases named in the same sentence as TRAF6 in open-access papers (continued):
Sharing a sentence is not in itself a finding about the gene and the disease.
diabetes (19 papers, 2011 to 2026). "Of note, a miR-146 deficiency in diabetes correlates with increased inflammation (for insufficient inhibition of IRAK1/TRAF6) and fibrosis (for expression of fibronectin)." (PMID 37685844, 2023). "But diabetes causes a significant increase in the expression of TRAF6 and IRAK1 (p<0.05) and NF-kB (p<0.01) genes in the diabetic group compared with the control group." (PMID 27123424, 2016). "The metabolic regulation of TRAF6 stability and its implications for downstream signaling can probably also contribute to smoldering inflammation that is associated with aging and metabolic diseases such as diabetes and obesity." (PMID 34298830, 2021). "Studies have shown that miR-146 expression in peripheral blood monocytes decreased significantly while TRAF-6 mRNA expression increased in patients with type 2 diabetes mellitus and miR-146 expression is negatively linked to TRAF-6 and NF-κB mRNA levels as well as circulating TNF-α and IL-6." (PMID 32337281, 2020). "Saponins also regulate the IRAK1/TRAF6 pathway by increasing the expression of miR‐146a, reducing inflammation, and improving diabetes by inhibiting the NF‐κB pathway." (PMID 41549047, 2026). "In mouse models of hyperlipidemia plus diabetes (db/db mice) or hypertension (1 mg/kg/d angiotensin-II for 7 days), TRAF6 inhibitor treatment (2.5 mg/kg/d for 7 or 14 days) normalized markers of oxidative stress and inflammation." (PMID 38554187, 2024). "For example, miR-146a was significantly upregulated during CVB3-infected mice and potentially modulated TLR3 and TRAF6 genes that control β cell activity in diabetes-induced inflammation." (PMID 39697323, 2024). "Previously, it has been shown an increase in protein expression of TLR-2, MyD88, and TRAF6 as well as NF-κB in human adipose tissue in states of obesity and diabetes mellitus type 2." (PMID 21266050, 2011). "Finally, human studies are needed to test the beneficial effects of TRAF6 inhibition in hypertension and diabetes." (PMID 38554187, 2024). "TRAF6 has been proved to be a miR-146a target in diabetes and lupus nephritis." (PMID 34670484, 2021). "In addition, complications that occur in diabetes and obesity of OPLL are suggested to be caused by the decreased transmission of TRAF6 to TAK1." (PMID 29782494, 2018). "In addition, TRAF6 is regulated by cytokines and toll-like receptors and may be involved, via the NF-κB pathway, in the progression of inflammation-related diseases such as diabetes." (PMID 39044893, 2024). "The results revealed that IRAK1, TRAF6, NUMB, and STX3 are direct targets of miR-146 in the context of diabetes." (PMID 37560309, 2023). "The analysis of individual studies on miR-146 in the context of diabetes yielded a heatmap that showcased the prevalence of several genes, namely IRAK1, TRAF6, IL-6, TNF-α, NUMB, EGFR, and TGFβ-1, among others." (PMID 37560309, 2023). "Swimming exercise, on the other hand, led to a substantial drop in the expression levels of miR-146a, NF-κB, and inflammatory cytokines and a significant rise in the expression levels of TRAF6 and IRAK1 in the exercise-diabetes group as compared to the diabetic group." (PMID 36911496, 2023). "Diabetes increased TLR4-mediated inflammation, whereas DP inhibited the protein expression of the TLR4 pathway (TLR4, Myd88, IRAK1, and TRAF6) and reduced the mRNA expressions of IL-1β, IL-1α, IL-6, and TNF-α and the protein expressions of TNF-α, IL-1β, and COX-2." (PMID 35463063, 2022). "The effect of CPP extract on various genes such as Pdx-1, Ins-1, ngn-3, GLUT-4, and IRS-1 in insulin signaling pathway and Traf-4, Traf-6, and Mapk-8 in MAPK downstream JNK cascade was examined through qRT-PCR to access the core molecular mechanism involved in CPP-induced recovery of diabetes." (PMID 32256963, 2020). "This process may contribute to the development of diabetes induced structural and functional changes and is mediated through NF-κB via IRAK1 and TRAF6." (PMID 28301595, 2017).
Obesity (19 papers, 2011 to 2025). Accumulation of substantial excess body fat. "We propose that during obesity, Ca2+ binding-led conformational changes in c-Cbl induce dissociation or altered association of c-Cbl and TRAF6, whereafter TAK1 competes with c-Cbl to bind to TRAF6, thereby facilitating and stabilizing the formation of the TRAF6-TAK1 complex." (PMID 36717580, 2023). "In addition, TRAF6 also plays a critical role in the activation of nuclear transcription factors associated with adipogenesis and obesity, such as NF-κB and AP-1." (PMID 34681631, 2021). "To further understand the effects of adipocyte-specific deletion of TRAF6 or TAK1 on HFD-induced obesity, we measured fat and lean tissue mass by performing DEXA." (PMID 29348847, 2017). "We next investigated the effects of adipocyte-specific deletion of TRAF6 or TAK1 in HFD-induced obesity." (PMID 29348847, 2017). "Collectively, these results suggest that while deletion of TRAF6 has a lessened impact in reducing obesity, TAK1 drastically reduces HFD-induced increase in adipose tissue mass, potentially through reducing adipocyte hypertrophy and survival." (PMID 29348847, 2017). "This indicates that pharmacological TRAF6 inhibition could be a target to prevent obesity related inflammation and metabolic complications." (PMID 36267276, 2022). "Interestingly, previous evidence has suggested that tumor necrosis factor (TNF), receptor-associated factor 6 (TRAF6), and enhancer of the zeste homolog 2 (EZH2) are key players in the upregulation of miR-429-3p in HFD-induced obesity." (PMID 34681631, 2021). "Since inflammation contributes significantly to HFD-induced obesity, the inhibition of TRAF6 signaling in inflammatory immune cells may be more effective in prevention of HFD-induced obesity as previously reported." (PMID 29348847, 2017). "In contrast, adipocyte-specific ablation of TRAF6 has a minimal effect on HFD-induced obesity." (PMID 29348847, 2017). "Interestingly, a significant reduction in wet weight and adipocyte hypertrophy was observe in epididymal WAT of adipocyte-specific TRAF6-KO mice on a high fat diet (HFD), which suggests TRAF6 inhibition in adipocytes could relieve the obesity induced by a HFD." (PMID 33531066, 2021). "Therefore, inhibiting TRAF6 expression reduce the accumulation of fat to relieve obesity." (PMID 33531066, 2021). "Therefore, it is suggested that enhancement of TRAF6 expression in obesity could increase degradation of EZH2, thereby promoting upregulation of miR-429-3p." (PMID 34681631, 2021). "However, it is not clear whether inhibiting TRAF6 to prevent obesity is caused by affecting adipocyte differentiation." (PMID 33531066, 2021). "TRAF6, an adaptor protein that possesses E3 ubiquitin ligase activity, is increased in HFD-induced obesity and increases ubiquitination and degradation of EZH2 to reduce EZH2 level." (PMID 34681631, 2021). "In this study, we investigated the role of TRAF6 and TAK1 in adipocyte formation and HFD-induced obesity." (PMID 29348847, 2017). "Our study suggests that TRAF6 and TAK1 differentially regulate adipocyte survival, white to beige adipocyte transition, and HFD-induced obesity." (PMID 29348847, 2017). "Using genetic mouse models, we investigated the effects of adipocyte-specific deletion of TRAF6 or TAK1 in the development of adipose tissue and HFD-induced obesity." (PMID 29348847, 2017). "The levels of TRAP, CTSK, RANKL/OPG, matrix metalloproteinase-9 (MMP-9), TRAF6, urinary hydroxyproline, and urinary calcium were increased in the obesity-prone rats after consuming a high-fat diet, which was not seen in the obesity-resistant rats." (PMID 38672518, 2024). "Finally, TRAF6 inhibition, in contrast to the inhibition of TRAF2/3/5, elicited protective effects in an experimental model for obesity-induced insulin resistance." (PMID 33198327, 2020). "Ablation of TRAF6 had a comparatively lessened impact on HFD-induced obesity and it did not affect the survival of adipocytes." (PMID 29348847, 2017).
Obesity (continued). "Collectively, our results suggest that even though TRAF6 is an upstream activator of TAK1 in many signaling cascades, inactivation of TAK1, but not TRAF6, regulates adipocyte survival, energy expenditure, and HFD-induced obesity in mice." (PMID 29348847, 2017). "We also compared the role of TRAF6 and TAK1 in HFD-induced obesity and glucose metabolism." (PMID 29348847, 2017). "We conclude that HFD induced obesity in C57BL/6 mice can lead to the occurrence of OA, and oral resveratrol may alleviate OA pathology by decreasing the levels of cytokines and/or through inhibiting TLR4/TRAF6 signaling pathways." (PMID 28250578, 2017). "Although TLRs and many other receptor-mediated signaling events activate TAK1 through the upstream activation of TRAF6, it remains unknown whether these two molecules have similar or distinct functions in the regulation of adipose tissue development and high-fat diet (HFD)-induced obesity." (PMID 29348847, 2017).
gastric cancer (18 papers, 2012 to 2025). A primary or metastatic malignant neoplasm involving the stomach. "Based on RNA-seq results, we suspected that MAPK, FOXO, and IL-17 signaling pathways can be associated with the promotion of growth and migration by TRAF6 in gastric cancer cells." (PMID 32724313, 2020). "Over expression of TRAF6 in muscles of gastric cancer were associated with TNM stage, level of serum albumin and percent of weight loss." (PMID 23013936, 2012). "Overexpression of TRAF6 in muscles of gastric cancer were associated with TNM stage, level of serum albumin and percent of weight loss (P > 0.05)." (PMID 23013936, 2012). "TRAF6 was significantly upregulated in muscle of gastric cancer compared with the control muscles, Overexpression of TRAF6 in muscle of gastric cancer were associated with TNM stage, the level of serum albumin and percent of weight loss." (PMID 23013936, 2012). "Here, we analyzed the prognostic significance of tumor necrosis factor receptor (TNFR)-associated factor 6 (TRAF6), and ubiquitin in gastric cancer patients." (PMID 23013936, 2012). "Furthermore, these results demonstrated that TRAF6 might be associated with the maintenance and generation of gastric cancer stem cells." (PMID 32724313, 2020). "Thus, TRAF6 might play a significant role in the cell cycle and be associated with gastric cancer genesis and development." (PMID 32724313, 2020). "Studies have confirmed that TRAF6 not only induces autophagy to regulate EMT of gastric cancer cells, but also affects CRC migration, invasion, and lymphatic metastasis through its ubiquitination site 124mut." (PMID 38135696, 2024). "The Cox proportional hazards model results suggested that high TRAF6 levels were related to gastric cancer radiosensitivity." (PMID 38169510, 2024). "TRAF6 augments the growth, proliferation, invasion, and migration of glioma cells and gastric cancer and inhibits their apoptosis." (PMID 36010884, 2022). "In summary, overexpression of TRAF6 promoted the proliferation and migration of gastric cancer cells." (PMID 32724313, 2020). "To further investigate the role of TRAF6 in gastric cancer, we knocked down the expression of TRAF6 by using siRNA." (PMID 32724313, 2020). "Gene ontology (GO) enrichment analysis in the NC and TRAF6 siRNA-2 groups was performed to explore possible mechanisms related to migration, proliferation, and stemness in gastric cancer cells." (PMID 32724313, 2020). "The inhibition of TRAF6 in BGC-823 gastric cancer cells, multiple myeloma cells, and human glioma cell lines can reduce proliferation, invasion, and migration and promote apoptosis, while the overexpression of TRAF6 shows the opposite effect." (PMID 33294443, 2020). "Crucially, overexpression of TRAF6 was confirmed to promote proliferation and migration, and TRAF6 knockdown reversed this phenomenon in gastric cancer cells." (PMID 32724313, 2020). "TRAF6 overexpression and knockdown experiments in the present study revealed that TRAF6 is highly expressed in gastric cancer tissues and promotes proliferation, migration, and stemness." (PMID 32724313, 2020). "Overexpression of TRAF6 enhanced proliferation and migration, and TRAF6 knockdown reversed this phenomenon in gastric cancer cells." (PMID 32724313, 2020). "TRAF6 was significantly upregulated in muscle of gastric cancer compared with the control muscles (P < 0.05)." (PMID 23013936, 2012). "Seventeen cases of gastric cancer had high expression of both TRAF6 and ubiquitin, and eight cases of gastric cancer had low expression of both TRAF6 and ubiquitin." (PMID 23013936, 2012). "The current study were to examine the expression of TRAF6 and ubiquitin in skeletal muscle specimens of patients with gastric cancer, to explore the possible correlation among TRAF6, ubiquitin mRNA expression and cachexia." (PMID 23013936, 2012). "We also examined TRAF6 expression in skeletal muscle with gastric cancer and its correlation with ubiquitin status." (PMID 23013936, 2012).
gastric cancer (continued). "However, another study has shown that miR-146b-5p is negatively correlated with lymph node metastasis and distant metastasis of gastric cancer and inhibits the malignant development of gastric cancer by targeting TRAF6." (PMID 35093110, 2022). "In conclusion, TRAF6 enhanced stemness but reduced differentiation; moreover, TRAF6 may promote EMT in gastric cancer cells." (PMID 32724313, 2020). "In conclusion, TRAF6 promotes proliferation, migration, and stemness in gastric cancer cells." (PMID 32724313, 2020). "In conclusion, TRAF6 is a significant factor promoting proliferation and migration in gastric cancer cells and may provide a new target for the accurate treatment of gastric cancer." (PMID 32724313, 2020). "In this study, abnormal expression of TRAF6 was found in gastric cancer tissues." (PMID 32724313, 2020). "Results confirmed that TRAF6 promoted the proliferation and migration of gastric cancer cells." (PMID 32724313, 2020). "Moreover, we demonstrated that FOXO, MAPK, and IL-17 signaling pathways are involved in the regulation of proliferation, migration, and stemness due to TRAF6 in gastric cancer cells." (PMID 32724313, 2020). "Fifty-three of 90 gastric cancers (58.9%) were found to overexpress TRAF6." (PMID 33294443, 2020). "In the present study, we revealed that TRAF6 plays a key role in gastric cancer." (PMID 32724313, 2020). "TRAF6 may regulate proliferation and migration of gastric cancer cells through the FOXO signaling pathway." (PMID 32724313, 2020). "Furthermore, the oncoprotein cag PAI of H. pylori activates NF-κB and induces IL-8 secretion through the TRAF2/TRAF6-NIK-IKK pathway in gastric cancer cells." (PMID 30294322, 2018). "Interestingly, a recent study on 102 gastric cancer patients showed that TRAF6 mRNA and protein, as well as ubiquitin mRNA and protein, were all upregulated in skeletal muscle tissue and correlated with disease stage and the degree of weight loss." (PMID 26856534, 2016). "Biopsies of the rectus abdominis muscle were obtained intra operatively from 102 gastric cancer patients and 29 subjects undergoing surgery for benign abdominal diseases, and muscle TRAF6 and ubiquitin mRNA expression and proteasome proteolytic activities were assessed." (PMID 23013936, 2012). "TRAF6 was significantly upregulated in muscle of gastric cancer compared with the control muscles." (PMID 23013936, 2012). "TRAF6 was upregulated in 67.65% (69/102) muscle of gastric cancer." (PMID 23013936, 2012). "The study showed overexpression of TRAF6 may play important role in gastric cancer cachexia." (PMID 23013936, 2012). "In this study, we confirmed TRAF6 elevated the expression of LC3 and it was essential to accelerating autophagy in gastric cancer cells." (PMID 32724313, 2020). "As supported by analyses of gastric cancer patient tissues and in vitro experiments using human gastric cancer cell lines BGC823 and SGC7901, TRIM59 promoted the degradation of TRAF6, a member of the TRAF family, via ubiquitination, thus inhibiting the NF-κB signaling pathway." (PMID 39768197, 2024). "miR-146a targets IRAK1 in gastric cancer cells, but not TRAF6." (PMID 22992343, 2012). "However, the exact effect of TRAF6 on gastric cancer stem cells has not been extensively studied." (PMID 32724313, 2020). "For instance, POU5F1 promotes gastric cancer (GC) cell proliferation and migration by inhibiting TRAF6 ubiquitination and degradation, thereby activating the NF-κB pathway, and KDM48 stimulates TRAF6-mediated AKT activation and facilitates the progression of rectal cancer." (PMID 40296903, 2025).
colon carcinoma (17 papers, 2016 to 2025). "The experimental results reveal the mechanism of CCL3 and TNF receptor-associated factor 6 (TRAF6)/NF-κB pathway-related factors and their effects on the proliferation of colon cancer cells." (PMID 35935327, 2022). "It has been demonstrated that overexpression of USP2 inhibited TLR/IL-1β-induced NF-κB activation through deubiquitination of tumor necrosis factor receptor-associated factor 6 (TRAF6) in human colon cancer cells." (PMID 32963492, 2020). "In contrast to CSN5, the deubiquitinase USP8 removes TNF receptor associated factor 6 (TRAF6)-mediated K63-linked ubiquitination, thereby promoting PD-L1 degradation in mouse models of lung and colon cancer." (PMID 35907881, 2022). "In colon cancer, TRAF6 activates the NF-κB/AP-1 signaling pathway by entering the nucleus, causing cancer cell growth." (PMID 36010884, 2022). "Colon tumor from LysM-tRXRα mice also showed a significant elevated level of TRAF6 expression, which positively correlated with STAT3 activation." (PMID 30931933, 2019). "In MC-38 tumor cells, TRAF6 influences colon cancer development under hypoxic conditions." (PMID 38169510, 2024). "TRAF6 exerts a significant role in the pathogenesis of colon cancer." (PMID 38169510, 2024). "It was inferred that TRAF6 may help colon cancer cells to proliferate by participating in cell division." (PMID 36604411, 2023). "It has been reported that GO nanoparticles trigger autophagy in colon carcinoma and macrophage leukemia cells through TLR4/TLR9-dependent activation of myeloid differentiation factor 88 (MyD88) and TNF receptor-associated factor 6 (TRAF6), initiating the subsequent nuclear translocation of NF-κB." (PMID 34439299, 2021). "In line with the in vivo data, knockdown of TRAF6 or inhibition of TRAF6 E3 ligase activity suppresses the survival, proliferation, migration, and metastasis of many human epithelial cancers, including breast, lung, liver, and colon cancers as well as HNSCC." (PMID 30294322, 2018). "In colon cancer, a deubiquitinating enzyme USP4 suppressed anti-tumor immune responses by deubiquitinating TRAF6 and IRF3, hindering the nuclear localization of the latter protein and thus inhibiting cellular interferon responses and antigen presentation." (PMID 40183093, 2025). "Besides, a preliminary study on the interaction between the target factor CCL3 and the differential pathway-related factors (TRAF6, NF-κB, and PI3K) in colon cancer cells was conducted." (PMID 35935327, 2022). "Reportedly, TRAF6 is a K63-E3 ubiquitin ligase that ubiquitinates and stabilizes HIF-1α in colon cancer cells independent of oxygen." (PMID 33142239, 2020).